GOLT1B (golgi transport 1B)
Description:
May be involved in fusion of ER-derived transport vesicles with the Golgi complex.
Synonyms: GCT2; CGI-141; YMR292W; GOT1; GOT1B
Tractability: Antibody: UniProt predicts a signal peptide or a membrane-spanning region. PROTAC: ubiquitination databases record sites on it; its protein half-life has been measured.
Gene: Protein-coding gene on chromosome 12 (21,501,781 to 21,518,408, forward strand). Ensembl gene ENSG00000111711.
Subcellular location: Golgi apparatus membrane
Subcellular location (Human Protein Atlas): Vesicles; Nucleoplasm
Gene Ontology:
Molecular function: protein binding
Biological process: positive regulation of canonical NF-kappaB signal transduction; endoplasmic reticulum to Golgi vesicle-mediated transport; retrograde transport, endosome to Golgi; vesicle-mediated transport
Cellular component: endoplasmic reticulum; membrane; protein-containing complex; cytoplasm; cytosol; endomembrane system; Golgi membrane
Homologues: Orthologues: chimpanzee GOLT1B (100% identical), guinea pig GOLT1B (100% identical), pig GOLT1B (100% identical), rabbit GOLT1B (100% identical), dog GOLT1B (99% identical), macaque GOLT1B (99% identical), rat Golt1b (99% identical), mouse Golt1b (99% identical), zebrafish golt1bb (88% identical), tropical clawed frog golt1b (85% identical), zebrafish golt1ba (82% identical), Drosophila melanogaster CG32576 (64% identical), and 23 more. Paralogues in human: GOLT1A (54% identical), DAGLB (26% identical), DAGLA (24% identical).
Diseases named in the same sentence as GOLT1B in open-access papers:
GOLT1B is named in the same sentence as 30 diseases in open-access papers, as found by Europe PMC text mining. Sharing a sentence is not in itself a finding about the gene and the disease. The quoted sentences say what the papers report.
colorectal cancer (5 papers, 2021 to 2023). A primary or metastatic malignant neoplasm that affects the colon or rectum. "Recent studies show that overexpression of GOLT1B in breast and colorectal cancer might be associated with poorer outcomes due to the promotion of immune evasion." (PMID 37174947, 2023). "On the other hand, GOLT1B also promotes the migration and invasion of colorectal cancer via inducing T lymphocyte apoptosis." (PMID 35127514, 2021). "Besides, high expression of GOLT1B suggests poor prognosis of colorectal cancer, and induces immunosuppression by promoting PD-L2 membrane localization." (PMID 35127514, 2021).
acute myeloid leukemia (2 papers, 2021 to 2023). Acute myeloid leukemia (AML) is a group of neoplasms arising from precursor cells committed to the myeloid cell-line differentiation. "Meanwhile, GOLT1B was significantly down-regulated in endometrial cancer (UCEC) and acute myeloid leukemia (LAML)." (PMID 35127514, 2021).
breast carcinoma (1 paper, 2021). "Since GOLT1B is potentially associated with the initiation and progression of breast cancer, we explored the relationship between GOLT1B mRNA expression and patient survival using the RNA-Seq datasets from TCGA." (PMID 35127514, 2021). "In this study, using RNA-Seq datasets of breast cancer patients from the public database (n = 1080), we revealed that GOLT1B, encoding a golgi vesicle transporter protein, was significantly higher expressed in human breast cancer tissues versus normal tissues." (PMID 35127514, 2021). "Therefore, to explore the potential mechanism underlying the up-regulation of GOLT1B in breast cancer, we performed a multi-omics analysis of the upstream transcriptional factors of GOLT1B." (PMID 35127514, 2021). "Therefore, we investigated the mutation types and frequency of GOLT1B in breast cancer using Cbioportal database (n = 9555)." (PMID 35127514, 2021). "Consistent with the previous report, our study revealed that the expression of GOLT1B was higher in breast cancer tissues than normal tissues." (PMID 35127514, 2021). "To clarify the correlation between the GOLT1B expression and clinical features of breast cancer, we studied GOLT1B mRNA expression in different groups using the UALCAN database." (PMID 35127514, 2021). "To explore the potential mechanism of GOLT1B in breast cancer, we investigated the influence of GOLT1B on the BRCA signatures." (PMID 35127514, 2021). "Next, to understand the pathways that GOLT1B potentially regulated in breast cancer, we analyzed all co-expressed proteins of GOLT1B using the datasets from the Linkomics database." (PMID 35127514, 2021). "As a result, the GOLT1B expression was negatively correlated with the OS in breast cancer patients with decreased infiltration of type 2 helper T cells, but not affect patients with enriched infiltration." (PMID 35127514, 2021). "Breast cancer patients with high GOLT1B expression had significantly lower survival rates than those patients with low GOLT1B expression." (PMID 35127514, 2021). "To sum up, we identified GOLT1B as a potential prognostic gene for breast cancer and disclosed its role in regulating the immune microenvironment." (PMID 35127514, 2021). "After analyzing the outcomes using Kaplan Meier database, we also revealed that breast cancer patients (n = 1089) with high expression of GOLT1B exhibited poorer OS, DMFS, and RFS." (PMID 35127514, 2021). "To further clarify the correlation between GOLT1B and immune microenvironment in breast cancer, we divided breast cancer patients into GOLT1B high-expressed and low-expressed groups." (PMID 35127514, 2021). "In our study, we found that GOLT1B was potentially a regulatory gene for the immune microenvironment of breast cancer patients and was closely related to the survival of patients." (PMID 35127514, 2021). "Focusing on breast cancer, we validated GOLT1B expression in breast cancer using GEPIA and UALCAN databases." (PMID 35127514, 2021). "Next, we further confirm the protein expression level of GOLT1B in breast cancer cell lines using western blotting." (PMID 35127514, 2021). "Analysis of breast cancer patients (n = 1084) showed that the OS, progression-free survival rate (PFI), and disease-specific survival rate (DSS) were lower in breast cancer patients expressing higher GOLT1B." (PMID 35127514, 2021). "Taken together, our study identified GOLT1B as a potential prognostic gene for breast cancer and demonstrated the functions of GOLT1B in immune microenvironment." (PMID 35127514, 2021). "In terms of age, breast cancer patients aged 21-40, 41-60, and 61-80 years expressed higher levels of GOLT1B than healthy people (P < 0.05)." (PMID 35127514, 2021). "Subsequently, to further clarify whether GOLT1B is one potential prognostic gene in human breast cancer, we analyzed other cohorts from prognoScan database and GEO." (PMID 35127514, 2021).
breast carcinoma (continued). "In terms of tumor subtypes, compared with luminal breast cancers, triple-negative type showed higher expression of GOLT1B (P < 0.0001), indicating that GOLT1B might be correlated with tumor malignancy." (PMID 35127514, 2021). "Besides, the GOLT1B expression was negatively correlated with the OS in breast cancer patients with enriched infiltration of regulatory T cells, but not affect patients with decreased infiltration." (PMID 35127514, 2021). "Finally, we disclosed the potential pathways involved in the functions of GOLT1B in breast cancer, including metabolism and ECM-receptor interaction pathways." (PMID 35127514, 2021). "Subsequently, we identified GOLT1B as a potential independent prognostic factor for breast cancer." (PMID 35127514, 2021). "Furthermore, we evaluated the expression of GOLT1B protein in breast cancer tissues and normal tissues using The Human Protein Atlas database." (PMID 35127514, 2021). "Our study proclaimed that the altered phosphorylation of two potential transcription factors of GOLT1B, JUN and SIN3A, might be responsible for the increased GOLT1B expression in breast cancer." (PMID 35127514, 2021). "Subsequently, to clarify whether GOLT1B is one potential prognostic gene in human breast cancer, we further analyzed other cohorts from prognoScan database and GEO." (PMID 35127514, 2021). "GOLT1B was also identified as a potential independent prognostic gene in breast cancer." (PMID 35127514, 2021). "Consequently, the corrected p values of OS (GSE1456), DSS (GSE1456) and RFS (GSE12276) were all less than 0.05, which additionally provided the possibility of GOLT1B as one prognostic gene in breast cancer." (PMID 35127514, 2021). "Besides, we verified GOLT1B expression in five breast cancer cell line using our original data and found GOLT1B was significantly up-regulated in MDA-MB-231, MCF-7, SKBR3." (PMID 35127514, 2021). "As a result, the univariate and multivariate Cox analyses identified GOLT1B as a potential independent prognostic gene for breast cancer, and it could be used in combination with other clinical diagnosis indicators to predict the prognosis of breast cancer." (PMID 35127514, 2021). "Consequently, the corrected p values of OS, DSS and RFS were all less than 0.05, supporting a possibility of GOLT1B as one prognostic gene in breast cancer." (PMID 35127514, 2021). "After a multi-omics analysis, we uncovered that the higher expression of GOLT1B in breast cancer tissues versus normal tissues might be due to the amplification of GOLT1B and altered phosphorylation of its potential transcriptional factors, including JUN and SIN3A." (PMID 35127514, 2021). "Therefore, GOLT1B may be involved in regulating and monitoring protein production in breast cancer, promoting protein synthesis and inhibiting protein degradation." (PMID 35127514, 2021). "Moreover, we revealed that GOLT1B might affect the overall survival rates of breast cancer through regulating the immune cell infiltration." (PMID 35127514, 2021). "As potential upstream regulators of GOLT1B, JUN and SIN3A have been gained increasing attention in diagnosis and treatment of breast cancer." (PMID 35127514, 2021). "The role of GOLT1B in breast cancer and its functions in immune microenvironment have not been disclosed." (PMID 35127514, 2021).
breast tumor (1 paper, 2021). "Meanwhile, we analyzed all co-expressed proteins of GOLT1B in breast tumor using the Linkomics database." (PMID 35127514, 2021).
diffuse large B-cell lymphoma (1 paper, 2023). "Using normal tissues as the controls, the expression of GOLT1B was found to be upregulated in the GTEx data set for diffuse large B-cell lymphoma (DLBC), skin cutaneous melanoma (SKCM), testicular germ cell tumors (TGCT), and thymoma (THYM) tissues." (PMID 38130634, 2023).
germ cell tumor (1 paper, 2023). A benign or malignant, gonadal or extragonadal neoplasm that originates from germ cells. "The highest alteration frequency of GOLT1B (> 8%) was observed in patients with non-seminomatous germ cell tumors, with amplification as a unique alteration type." (PMID 38130634, 2023). "Furthermore, the highest amplification frequency of GOLT1B was identified in tumors of the reproductive system, particularly in nonseminomatous germ cell tumors (> 8%)." (PMID 38130634, 2023).
glioma (1 paper, 2020). A benign or malignant brain and spinal cord tumor that arises from glial cells (astrocytes, oligodendrocytes, ependymal cells). "Here, AK2, CYB5A and GOLT1B were significantly higher in all glioma sample groups, relative to controls." (PMID 32635403, 2020).
hepatitis B (1 paper, 2021). "Finally, in support of our conclusions regarding the role of GOLT1B in hepatic tumorigenesis, its expression was significantly higher in the tumor compared with non-tumoral tissues of both hepatitis B and hepatitis C patients." (PMID 35055994, 2021).
lung adenocarcinoma (1 paper, 2024). A carcinoma that arises from the lung and is characterized by the presence of malignant glandular epithelial cells. "GOLT1B promotes the peptide transport in macrophages of OP, which is also correlated with a worse prognosis in lung adenocarcinoma." (PMID 39083563, 2024).
lung carcinoma (1 paper, 2023). "Golgi transport 1B (GOLT1B) has been associated with cellular malignant behaviors and immune responses in colorectal and lung cancer, but a systematic pan-cancer analysis on GOLT1B has not been conducted." (PMID 38130634, 2023).
lymph node metastases (1 paper, 2021). "In terms of lymph node metastases, GOLT1B was lower expressed in patients classified as N3 than in N0, N1, and N2 patients (P = 0.032, P = 0.033, P = 0.026)." (PMID 35127514, 2021).
melanoma (1 paper, 2024). A malignant, usually aggressive tumor composed of atypical, neoplastic melanocytes. "Our functional esiRNA screen identified five candidate translation targets of VARS (that is, HADH, KIF13B, SLC7A5, QDPR and GOLT1B), whose depletion re-sensitizes resistant melanoma cells to MAPK therapy." (PMID 38849541, 2024).
tumor (9 papers, 2020 to 2025). "The box plots showed that higher levels of GOLT1B expression were associated with higher tumor stages in ACC, BLCA, LUAD, and UCS." (PMID 38130634, 2023). "Based on the analysis of online database TIMER (Tumor IMmune Estimation Resource), we found that GOLT1B was significantly associated with the infiltration of CD4+ T cells, CD8+ T cells and macrophages." (PMID 34059062, 2021). "The study provided a comprehensive understanding of the oncogenic role of GOLT1B, highlighting a potential mechanism whereby GOLT1B influences the tumor microenvironment, as well as cancer immunotherapy." (PMID 38941397, 2024). "This pan-cancer analysis provided a comprehensive understanding of the oncogenic role of GOLT1B, highlighting a potential mechanism whereby GOLT1B influences the tumor microenvironment, as well as cancer immunotherapy." (PMID 38130634, 2023). "The pooled analysis confirmed that, compared with normal tissues, the transcriptional levels of GOLT1B were significantly elevated in tumor tissues." (PMID 38130634, 2023). "The genetic alteration status of GOLT1B in different tumor samples from TCGA cohorts was investigated by applying cBioPortal." (PMID 38130634, 2023). "After combining all tumor expression data from TCGA using the GEPIA2 tool, the top 100 genes associated with GOLT1B expression were selected." (PMID 38130634, 2023). "IHC examination on tumor tissue microarray of 224 CRC patients showed that GOLT1B is positively stained in the tumor area of most patients." (PMID 34059062, 2021). "In vivo targeted delivery of GOLT1B-siRNA was investigated in PDX (Patient derived tumor xenograft) model." (PMID 34059062, 2021). "Subsequently, we discovered that GOLT1B potentially regulated the immune microenvironment basing on the finding that its expression was closely related to the tumor microenvironment score and infiltration of immune cells." (PMID 35127514, 2021). "The IHC and HE staining showed that after siGOLT1B treatment, the expression level of GOLT1B in the tumor was significantly reduced." (PMID 34059062, 2021). "Based on these results, we believe that GOLT1B can promote immune escape by increasing the expression level of PD-L2 in cancer cells and promoting apoptosis of T lymphocytes in the tumor microenvironment, which further promotes the metastasis of CRC." (PMID 34059062, 2021). "Consistently, GOLT1B level were significantly higher in tumor tissues compared with that in paired normal tissue (P < 0.01)." (PMID 34059062, 2021). "The link between the Golgi apparatus and tumor invasion and metastasis has beenextensively researched, with a particular emphasis on its involvement in CRC.Experimental studies have revealed that Golgi transport 1B (GOLT1B) encodes thevesicle transporter of the Golgi apparatus (Liu etal., 2021)." (PMID 41020586, 2025). "GOLT1B upregulates PD-L2 and promotes T lymphocyte apoptosis in the tumor microenvironment." (PMID 38982223, 2024). "Recent reports regarding the role of GOLT1B in immune evasion let us investigate whether our 2-PS correlated with the estimated fractions of immune cells within the tumor tissue." (PMID 37174947, 2023). "Furthermore, the protein expression profiles of GOLT1B in various tumor and normal tissues were assessed using the CPTAC database." (PMID 38130634, 2023). "Limited studies have reported the oncogenic role of GOLT1B in human cancers. sCNA is a major source of genomic variations driving tumor evolution, and sCNA screening may identify prognostic biomarkers." (PMID 38130634, 2023). "Further, targeted delivery of GOLT1B siRNA could significantly inhibit tumor progression in GOLT1B highly expressed PDX model." (PMID 34059062, 2021). "Accordingly, our in vitro and in vivo experiments showed that GOLT1B is correlated with cell proliferation, targeting GOLT1B could suppress the tumor growth in PDX model." (PMID 34059062, 2021).
tumor (continued). "Furthermore, to confirm that GOLT1B affects tumor progression by regulating the immune microenvironment, we studied the effect of GOLT1B expression on the OS of patients with high/low immune cell infiltration using the Kaplan-Meier Plotter database." (PMID 35127514, 2021). "In the subnetwork related to tumor progression, the hubs from the blue module are the most connected, such as the genes Cmas, Kmt2a, Golt1b, Cdc34, Manf, Sco1, and Thoc3, followed by hubs from the light cyan (Extl2, Commd3, Wdr41, Keap1, Osbpl9) and pink modules." (PMID 32831131, 2020). "Therefore, we speculated that GOLT1B might be involved in the tumor immune response." (PMID 34059062, 2021). "Our study showed that high expression of GOLT1B induced the increase of PD-L2 expression in CRC cells, which could induce the apoptosis of tumor-infiltrating T lymphocytes and inhibit the level of IFNγ." (PMID 34059062, 2021). "In order to verify whether targeting GOLT1B can suppress cancer progression, CRC PDX model were established, and then siGOLT1B were intraperitoneally injected 4 weeks after tumor inoculation." (PMID 34059062, 2021). "Taken together, GOLT1B may promote CRC metastasis not only by activating the downstream Wnt/β-catenin signaling, but also by facilitating the membrane localization of PD-L2 to induce T lymphocytes apoptosis and thus reshape the tumor microenvironment." (PMID 34059062, 2021).